SDHA (succinate dehydrogenase complex flavoprotein subunit A)
Diseases named in the same sentence as SDHA in open-access papers (continued):
Sharing a sentence is not in itself a finding about the gene and the disease.
tumor (continued). "SDHA as a catalytic subunit of SDH, and its expression and activity, are tightly regulated by oncogenes or tumor suppressors." (PMID 36232604, 2022). "Paclitaxel and shikonin showed a similar anti-tumor activity against (OVCAR3 cell lines +/− SDHA), however shikonin was significantly more potent in killing Caov3-SDHA cells than paclitaxel." (PMID 36291881, 2022). "Accordingly, we observed up-regulation of the Succinate dehydrogenase complex, a tetramer consisting of SDHA, SDHB, SDHC and SDHD subunits that exerts a critical tumor suppressive role and has been proposed as an important therapeutic target in HCC." (PMID 36203462, 2022). "Blocking the expression of succinate dehydrogenase complex flavoprotein subunit A (SDHA) and oxidative phosphorylation activities of macrophages with dimethyl malonate treatment exhibited markedly delayed tumor growth." (PMID 34267763, 2021). "A prominent example is the drop in the tumor suppressor succinate dehydrogenase (SDHA and SDHB) with the increasing tumor size." (PMID 33924061, 2021). "Analogous to in vitro results, both ONC201 and GsON201 decreased the abundance of SDHA, the phosphorylation of pT202/Y204ERK, and pS2448mTOR in both tumor and control tissue compared to vehicle-treated controls." (PMID 34988452, 2021). "In the present study, the levels of SDHA, UQCRC2, MT-CO1 and ATP5F1A were significantly reduced in the tumor periphery compared to the control tissue." (PMID 31167495, 2019). "Some of these amplified genes are well-known tumor related genes, such as AKT2, FGFR3, FGF10, SDHA, CCNE1, PI3KCA, and etc." (PMID 28029662, 2017). "This would be a requirement specific for SDHD, as tumor development in SDHB, SDHC and SDHA appear to follow a two-hit kinetics." (PMID 24465590, 2014). "This may point to a lack of penetrance of SDHA mutations in initiating PGL/PHEO neoplasms." (PMID 23730622, 2013). "Succinate cytochrome c reductase activity (SCCR, complex II + III) was measured in tumor homogenates: individual SDHB and SDHA protein expression followed SDH enzymatic activity." (PMID 19763184, 2009). "SDHA was downregulated in HCC tumor tissues and showed a negative correlation with M2 macrophage infiltration." (PMID 41613800, 2026). "The overall median follow-up period of the subjects without a tumor was 5.54 years (1.08–17.7); 4.09 years (3.00–5.17) for SDHA, 5.92 years (2.33–13.33) for SDHB, and 4.83 years (1.08–17.17) for SDHD variant carriers." (PMID 39881751, 2025). "Most individuals with a PGV in SDHA (henceforth referred to as SDHA PGV carriers) present with an apparently sporadic tumour without relevant family history, and most PGVs are inherited from a parent who has not presented with any clinical features." (PMID 35260474, 2023). "SDHA-negative samples were sequenced both in corresponding tumor and germline DNA isolated from paraffin-embedded healthy tissue surrounding the tumor; four cases were germline." (PMID 36980917, 2023). "With increasing implementation of tumour and germline large panel and whole-genome sequencing, it is likely more SDHA PGV carriers will be identified in patients with tumours not strongly associated with SDHA, or outside the context of a strong family history." (PMID 35260474, 2023). "When an SDHA PGV is identified during tumour analysis, the likelihood of it being of germline origin is high in both on-tumour (associated tumour types) and off-tumour (non-associated tumour types) settings." (PMID 35260474, 2023). "Circulating succinate was elevated in patients with head and neck squamous cell carcinoma, along with increased expression of SUCNR1, HIF1α, SDHA and SDHB in the tumor tissue relative to matched normal mucosa, further highlighting a role of succinate as oncometabolite." (PMID 36551845, 2022). "SDHA staining was retained whilst SDHB expression was reportedly heterogeneous from intensely positive immunostaining in some tumour cells to absent protein expression in others; no LOH was identified." (PMID 35938916, 2022).
tumor (continued). "Our work demonstrates that targeting metabolic enzymes (SDHA, cPLA2, HK2) with specific inhibitors (EPIC, AA and 2-DG) could extremely decrease the ATP production rate in GBM cells, leading to tumor cell proliferation inhibition." (PMID 36276638, 2022). "Tumour cells lacked SDHB staining at IHC but expressed SDHA; preserved SDHA IHC being a recognised phenomenon in SDHB, SDHC and SDHD pathogenic variants." (PMID 35938916, 2022). "Tumour tissue showed no SDHB and SDHA expression alongside LOH, suggesting the SDHA variant was contributory." (PMID 35938916, 2022). "Immunohistochemically, tumor cells in SDHB-, SDHC-, and SDHD-deficient RCC are negative for SDHB but positive for SDHA." (PMID 35869040, 2022). "For a subset of the cancer predisposition genes, such as SDHA and SDHB (encoding for mitochondrial enzymes), none of the tumours showed chromothripsis, despite a secondary somatic hit in all cases (n = 5)." (PMID 32385320, 2020). "In addition, we found that valine and proline, two essential aminoacids, were increased in tumor tissues, implying that the TCA cycle was supported by the glucogenic SDHA and valine/proline increase." (PMID 33014287, 2020). "The SDHA labeling for PCC1 also appeared to be negative for the tumor cells in this PCC, while all other tumors were positive." (PMID 31052272, 2019). "To evaluate whether the Ala45Thr variant was associated with changes in expression of these proteins, we used immunohistochemistry (IHC) to assess SDHA and SDHB protein levels in normal renal and RCC tumor tissue from the female proband." (PMID 30680959, 2019). "SDH genes (SDHA, SDHB, SDHC, SDHD) act as classical tumor suppressors, such that germline heterozygous inactivating mutations coupled with somatic loss of the remaining wild-type allele leads to complete loss of enzyme function and development of associated tumors." (PMID 28738844, 2017). "However, an increase in the number of CNA events was observed from low‐grade to high‐grade tumours, especially for concomitant gains of TERT, SDHA and RICTOR located on the p‐arm of chromosome 5." (PMID 27873319, 2017). "In analysis of correlation between metabolism-related protein expression in tumor and stroma, there was a significant correlation in SDHB (T) and SDHB (S) (r = 0.309, p = 0.006), SDHB (T) and SDHA (S) (r = 0.290, p = 0.011), and SDHB (T) and ATP synthase (S) (r = 0.235, p = 0.039)." (PMID 24387319, 2014). "Although tumor cells show increased OXPHOS-related enzymes (SDHA, SDHB, ATP-synthase) no apoptotic activity (AI < 10%) in cancer cells was observed in those highly metabolic active regions." (PMID 25048361, 2014). "The HER-2 tumor subtype showed the highest frequency of high SDHA expression, and the luminal A subtype most frequently showed low or negative SDHA expression (P = 0.032)." (PMID 23888270, 2013). "Tumour-derived DNA from his GIST demonstrated a somatic PDGFRA driver mutation, and SDH staining was preserved, indicating a sporadic PDGFRA-driven GIST rather than a classical SDHA-deficient tumour." (PMID 41635891, 2026). "Accordingly, cascade testing of the SDHA variant was not recommended in his family, and no surveillance for SDH-associated tumours was initiated, although we recognise that some international guidelines may take a more precautionary approach." (PMID 41635891, 2026). "Similarly, as in the pilot study, the SDHA-overexpressing tumors (BPPNM) showed increased tumorigenic potential reflected as rapid tumor development and spreading when compared with low-SDHA tumors (SPCA) or BPPNM-SDHA-KD, which significantly reduced mouse survival." (PMID 40563592, 2025). "In contrast, tumor cells are negative for both SDHA and SDHB in SDHA-deficient RCC1." (PMID 35869040, 2022). "SDHA was expressed in all tumor cells, regardless of whether the cells were positive or negative for SDHB gene mutations." (PMID 35300626, 2022).
tumor (continued). "Thus, even a 50% reduction in SDHA protein levels, as a result of heterozygous mutations, would not compromise the SDH function in paraganglia to initiate tumor formation." (PMID 17376234, 2007). "Organs from an egg without a tumor were used to test eight primers for cross‐reactivity with the chicken cells, namely B2M, HMBS, ALTB, TBP, SDHA, YWHAZ, and UBC." (PMID 40443053, 2025). "The tumor was histologically composed of oncocytic cells that expressed KRT7, vimentin, SDHA, SDHB and fumarate hydratase, but not KIT, GATA3 and alpha-methylacyl-CoA racemase." (PMID 39980061, 2025). "In the Netherlands, observed putative PGVs in dominant genes that do not match the tumor type (ATR, CHEK2 (3x), SDHA and MITF) are normally not reported back to the patient, except if there is a matching personal and/or familial history." (PMID 41168197, 2025). "Consistently, blocking SDHA expression and oxidative phosphorylation activities of macrophages with DMM treatment significantly downregulated the CD206 expressions and MFI of macrophages, but not IL-10 expression in tumor-bearing mice." (PMID 32596169, 2020). "(ii) The physical interaction between the SDHA protein product and the PGL module is loose and kinetically fast during catalysis, thus a mutant SDHA protein product could not irreversibly trap a PGL module to initiate tumor formation." (PMID 17376234, 2007).
cancer (74 papers, 2012 to 2026). A tumor composed of atypical neoplastic, often pleomorphic cells that invade other tissues. "Our previous in vitro drug screening study revealed that the most selective and potent compound in targeting SDHA-overexpressing cancer cells is shikonin; however, the underlying mechanism is unclear." (PMID 40563592, 2025). "More importantly, measuring autofluorescence (within the FAD spectral region) from SDHA (recovered by immunoprecipitation) confirmed reduced fluorescence in OSCC than in non-cancer cells, suggesting flavinated SDHA is responsible for loss of autofluorescence." (PMID 37945749, 2023). "It has previously been reported that mitochondrial function is essential for cancer cell viability and that mutations in SDHA, FH, and IDH1 can change mitochondrial metabolism and allow cancer cells to adapt to changing environments." (PMID 37190292, 2023). "Further, our work demonstrated that SDHA overexpression is associated with a generation of significantly more and larger cancer cell colonies in anchorage-independent conditions." (PMID 36291881, 2022). "Two GISTs were observed amongst ten SDHA germline variant carriers found through agnostic cancer genetic testing and four GISTs occurred in 15 carriers identified through a review of UK genetic testing laboratory reports." (PMID 33854214, 2021). "Germline mutations in known cancer predisposition genes were predicted in 13 (30%) of CA-Pheo and 38 (45%) of CA-Para cases, predominantly involving SDHA/B genes." (PMID 34282751, 2021). "Variant filtering based on a list of 83 cancer predisposition genes and variant assessment according to American College of Medical Genetics criteria revealed a nonsense variant in SDHA (c.1534C>T (p.Arg512*)) in both individuals." (PMID 33854214, 2021). "The loss of SDHA has been shown to be an oncogenic event, manifested by both benign and malignant tumors." (PMID 32046305, 2020). "We have provided several lines for evidence to support our finding that this SDHA variant has a correlation between the development of true sporadic PGL or potentially relevant cancer." (PMID 33031286, 2020). "The acetylation-impacting genes, IDH2, SDHA/B/C, and FH, are annotated as being frequently mutated in cancers in the COSMIC database." (PMID 30823893, 2019). "Through targeted sequencing, one predicted pathogenic missense mutation was identified in SDHA, a known cancer predisposition gene, in a patient diagnosed with epitheloid sarcoma at 24-years-old." (PMID 28878254, 2017). "While SDHA is typically associated with mitochondrial respiration, its overexpression under stress conditions has been linked to ROS amplification and apoptosis in cancer cells." (PMID 40746891, 2025). "Collectively, these findings revealed a previously unrecognized metabolic axis linking SDH activity to the de novo synthesis of both purines and pyrimidines, while functional assays demonstrated that SDHA loss or pharmacological inhibition leads to growth defects across diverse cancer models." (PMID 40060604, 2025). "More studies on tumors, patients, and families are needed to inform whether SDHA pathogenic variants are associated with a specific cancer risk profile compared with SDHB, SDHD, or SDHC." (PMID 38885448, 2024). "SdhA mutations mostly cause clinical outcomes reminiscent of other mitochondrial diseases, while loss of function of any of the other subunits mostly causes a cancer phenotype." (PMID 35563430, 2022). "SDHA has recently been shown to inhibit canonical WNT signaling, and consequently the proliferation and invasion of cancer cells, suggesting that the loss of SDHA in CRLM could be linked to hyperactive WNT signaling." (PMID 35565214, 2022).
cancer (continued). "Therefore, both the proband and his mother were considered at risk for developing these cancers and routine screening following the criteria specified for SDHA positive individuals was initiated." (PMID 33960148, 2021). "Interestingly, pathogenic variants in SDHA have been implicated in cancer and mitochondrial disease." (PMID 33960148, 2021). "Integrated analysis of public databases and structural predictions indicated that the two affected individuals also had additional variants in genes including TGFB2, TRAP1, PARP1, and EGF, each potentially relevant to cancer risk alone or in conjunction with the SDHA variant." (PMID 30680959, 2019). "Hence, it can be inferred that detecting SDHA gene expression may have diagnostic and prognostic value in certain cancers." (PMID 40119440, 2025). "The expression of both LRPPRC and SDHA was very low in normal fallopian tubes when compared with cancer samples." (PMID 40563592, 2025). "For example, individuals can be monitored and regularly screened for cancer-related phenotypes associated with CHEK2 and STK11 (individual 1) and SDHA (individual 4)." (PMID 40195116, 2025). "SDHA overexpression and siSDHA were transiently transfected into the cancer cells separately to assess expression levels, cellular proliferation, and migration dynamics through colony formation assay, CCK8 assay, wound-healing analysis." (PMID 40119440, 2025). "It is likely that normal cells or cancer cells with normal SDHA levels are able to preserve mitochondrial integrity and the ETC function by employing mitochondrial hyperfusion." (PMID 40563592, 2025). "This analysis highlights SDHA as a potential regulator of nucleotide synthesis, linking mitochondrial metabolism to the biosynthetic needs of proliferating cancer cells." (PMID 40060604, 2025). "Conversely, the overexpression of SDHA substantially promoted cancer cell proliferation and metastasis." (PMID 40119440, 2025). "It is important to consider the individual patient characteristics and the heterogeneity of BC when assessing the influence of SDHA upregulation on cancer progression." (PMID 40119440, 2025). "One study from an academic cancer center investigated the frequency of germline SDHA PV (n = 10) in a cohort of ~5000 patients with solid tumors." (PMID 38770192, 2024). "Mutations in cancer-related genes (KMT2C, NOTCH2, PRKAR1A, SDHA, and USP6) and genes related to EC (ARID1A, CTNNB1, PIK3CA, and PTEN) were identified with high frequencies among the three samples." (PMID 35626111, 2022). "In our study, the metabolic disorder in NSCLC was demonstrated by elevated expression levels of G6PD and SDHA in carcinoma tissues than in paired para-carcinoma tissues." (PMID 34150616, 2021). "SDHA mRNA expression was assessed across multiple cancer types." (PMID 40119440, 2025). "This also emphasizes the idea that LRPPRC inhibitors could be less toxic to normal cells while eliminating SDHA/LRPPRC-overexpressing cancer cells." (PMID 40563592, 2025). "Using TCGA data, we have found that the overall risk of elevated SDHA and SDHB expression is cancer dependent, suggesting that complex II targeting may be more tissue selective and may broaden the therapeutic window." (PMID 41350470, 2025). "For six genes [ELP1, GPR161, VHL and SDHA/B/C], a clear lack of mutational constraint calls the pediatric penetrance and/or severity of associated cancers into question." (PMID 38424437, 2024). "Larger studies are needed to rule out possible associations of SDHA PVs with other cancer types beyond what is currently described." (PMID 38770192, 2024). "A high expression of SDHA and NUP210 were positively associated with the unfavorable prognosis of AML patients and an elevated expression of SLC27A4 was linked to poorer clinical outcomes in several cancer types." (PMID 38254953, 2023). "It has been demonstrated that SDHA proteins play a pivotal role in cancer cell growth." (PMID 36232604, 2022).